SDC1 (syndecan 1)
Diseases named in the same sentence as SDC1 in open-access papers (continued):
Sharing a sentence is not in itself a finding about the gene and the disease.
atherosclerosis (continued). "However, other authors found a protective role of syndecan-1 in atherosclerosis, based mainly on its well-established anti-inflammatory functions." (PMID 31815014, 2019). "However, there is still room to debate as to syndecan-1's precise role in ischemic heart failure, given the fact that it also accelerates atherosclerosis." (PMID 31815014, 2019). "Additionally, increased circulating syndecan-1 levels could help slow the progression of subclinical atherosclerosis." (PMID 41578772, 2025). "Crosstalk occurring between syndecan-1 and syndecan-4 expressions, i.e., upregulation of syndecan-4 expression by downregulation of syndecan-1 expression under certain conditions in atherosclerosis may be one of the factors responsible for atherosclerosis progression." (PMID 33997316, 2021). "Our findings provide insights into a novel class of cell-surface receptors responsible for vSMC differentiation and suggest that the preservation or enhancement of syndecan-1 expression may be a potential therapeutic target capable of altering the course of in-stent restenosis and atherosclerosis." (PMID 24587062, 2014). "Sdc1 was enriched in the ‘ECM-receptor interaction’, ‘Fluid shear stress and atherosclerosis’ and ‘Proteoglycans in cancer’ pathways." (PMID 40497967, 2025). "Furthermore, acute cardiovascular events increased serum SDC1, further supporting the hypothesis of shedding as responsible for a reduced glycocalyx expression in coronary artery disease, mainly in acute disorders or advanced atherosclerosis." (PMID 37511353, 2023). "A previous study indicated that blood concentrations of Sdc-1 and heparan sulfate (GCX components) are high in patients undergoing dialysis, and the relationship between atherosclerosis and GCX damage has also been reported." (PMID 34796208, 2021). "A process of compensation (or redundancy) displayed by other PGs expression in the present model could explain the absence of a SDC-1 specific effect, as it has been reported in the context of atherosclerosis between biglycan and perlecan for Apo-B retention." (PMID 35548440, 2022). "Similarly, syndecan-1 is required to maintain the motility of macrophages during chronic inflammation in atherosclerosis, where the absence of syndecan-1 resulted in persistent inflammation." (PMID 32133006, 2020). "In ECs, expression of various HS-proteoglycans is known, including SDC1, 2, 4, and GPC1, 3, 4, but their role in atherosclerosis has not been adequately described thus far." (PMID 37511353, 2023).
dengue (17 papers, 2011 to 2025). "Exploring therapeutic strategies to prevent further damage to, or accelerate restoration of the glycocalyx layer may help to reduce morbidity associated with plasma leak in dengue; SDC1 and/or PBR hf may serve as useful surrogate endpoints in future clinical trials." (PMID 33178710, 2020). "The pre-fluid resuscitation values of Syndecan-1, Hyaluronan, Ferritin, and ST-2 (measured at presentation with shock) in our study are higher than the values reported by other dengue studies, which is likely explained by more severe disease in our cohort." (PMID 39193474, 2024). "Within the dengue shock group, although all of the glycocalyx biomarkers were positively associated with SOFA score at enrolment, only syndecan-1 was associated with ICU admission (p<0.001) and mortality (p<0.001)." (PMID 38536887, 2024). "A recent study analyzing the expression of endoglin (EDG) and Syndecan-1 (SDC1) from activated endothelial cells during plasma leakage in critical phase of dengue showed significant correlation in predicting dengue severity." (PMID 35055629, 2022). "We investigated the association of 10 biomarkers (VCAM-1, SDC-1, Ang-2, IL-8, IP-10, IL-1RA, sCD163, sTREM-1, ferritin, CRP) with the development of severe/moderate dengue (S/MD)." (PMID 34154705, 2021). "In summary, our study shows that plasma HPSE activity as well as the endothelial glycocalyx degradation products, HS and syndecan-1, are increased in acute dengue patients." (PMID 34987504, 2021). "Previous clinical studies in dengue patients have described the increase of endothelial glycocalyx degradation products such as heparan sulfate, hyaluronic acid and shedded syndecan-1 in plasma." (PMID 34987504, 2021). "Heparanase activity (plasma and urine), and heparan sulfate and syndecan-1 (plasma levels) were measured in dengue patients with thrombocytopenia in acute phase (n=30), during course of disease (n=10) and in convalescent phase (n=25)." (PMID 34987504, 2021). "With respect to the endothelial glycocalyx, we found that broad injury to the glycocalyx occurs in dengue shock, with elevated heparan sulfate, hyaluronan and SDC-1 in dengue shock versus healthy controls; however heparan sulfate levels were markedly higher in the septic shock group." (PMID 38536887, 2024). "Similarly, glycocalyx components, such as heparan sulfate and syndecan-1, were increased in acute dengue and restored during convalescence." (PMID 34987504, 2021). "Furthermore, increased blood levels of HA, syndecan-1 and CS in dengue patients were proportional to disease severity, further suggesting that EGL is damaged in clinical disease." (PMID 34882753, 2021). "Similarly, syndecan-1 plasma levels (n=30) were increased in acute dengue compared to convalescent dengue, and highest at hospital admission, whereafter they decreased to normal levels (n=10)." (PMID 34987504, 2021). "A possible reason for targeted SDC1 shedding over endocan could be related to dengue viral binding to heparan sulfate (HS), SDC1's GAG side chain." (PMID 33178710, 2020). "In this study, we observed that among NS1, MIF and glycocalyx degradation-related molecules, the HPA-1, metalloproteinase 9 (MMP-9) and syndecan 1 (CD138) serum levels were all increased in dengue patients, and only NS1 and MIF showed a positive correlation with the CD138 level in severe patients." (PMID 29702687, 2018). "Evidence of reduced glycocalyx thickness together with increased plasma concentrations of EGL fragments, such as Syndecan-1, Heparan Sulfate, and Hyaluronan, in dengue patients suggests these products may be useful biomarkers and surrogates of leakage severity." (PMID 39193474, 2024). "In conclusion, higher levels of the ten biomarkers (VCAM-1, SDC-1, Ang-2, IL-8, IP-10, IL-1RA, sCD163, sTREM-1, ferritin, and CRP), when considered individually, are associated with increased risk of adverse clinical outcomes in both children and adults with dengue." (PMID 34154705, 2021).
dengue (continued). "In a murine dengue model, inhibition of MIF abolished NS-1-induced MMP-9 secretion, and this correlated with reduced syndecan-1 shedding, suggesting that MIF is an important factor that mediates vascular pathology in DENV infection." (PMID 34882753, 2021). "A systematic review and meta-analysis identified key biomarkers predictive of severe dengue manifestations, including elevated levels of CRP, AST, IL-8, and decreased albumin levels for DHF, and increased levels of VCAM-1, syndecan-1, AST, and CRP for severe dengue (SD)." (PMID 40100920, 2025). "The authors observed a steady and significant increase in the levels of protein and mRNA of both the endoglin and syndecan-1 towards defervescence which is considered a critical phase in both severe and non-severe dengue cases." (PMID 35631030, 2022). "More recently, endoglin and syndecan-1 were quantified the mRNA expression and soluble protein levels in dengue cases during febrile, defervescence, and convalescence stages in DF, DFWS, and severe cases compared to non-dengue Other Febrile Illness (OFI) and healthy control." (PMID 35631030, 2022).
squamous cell carcinoma (16 papers, 1994 to 2025). A carcinoma arising from squamous epithelial cells. "Overexpression of Sdc1 is linked to basal and squamous cell carcinomas, a metastatic type of human skin cancer." (PMID 36009225, 2022). "For example, syndecan-1 expression was found mainly in epithelial cells and reduced during malignant transformation of various epithelia, and this loss correlated with the histological differentiation grade of squamous cell carcinomas of the head and neck." (PMID 23691363, 2013). "The expression of syndecan-1 and E-cadherin was studied in 47 canine squamous cell carcinoma using immunohistochemistry." (PMID 39728992, 2024). "Interaction of SDC1 and α6β4 integrin cytoplasmic domains would regulate ErbB2-mediated integrin activation in human squamous carcinoma cells." (PMID 32756007, 2020). "High levels of SDC1 have been detected in squamous cell carcinomas such as those from cervix uteri and esophagus, in invasive urothelial cancer, and lung cancer." (PMID 32916872, 2020). "On the other hand, the interaction of the SDC1 cytoplasmic domain with the laminin receptor α6β4 integrin regulates ErbB2 tyrosine kinase activation leading to human squamous carcinoma cell spreading." (PMID 32916872, 2020). "We have studied the prognostic significance of syndecan-1 expression in squamous cell carcinoma (SCC) of the head and neck treated with surgery and post-operative radiotherapy." (PMID 10027330, 1999). "Syndecan-1 expression is induced during keratinocyte differentiation and reduced during the formation of squamous cell carcinomas (SCCs)." (PMID 8054282, 1994). "However, stromal syndecan-1 expression has also been observed in human squamous cell carcinoma cases." (PMID 39728992, 2024). "In human squamous cell carcinoma, syndecan-1 and E-cadherin have shown promise as markers." (PMID 39728992, 2024). "Syndecan-1 also plays a role in squamous cell carcinoma collagen-mediated motility and invasion by modulating RhoA and Rac activity, suggesting that decreased syndecan-1 expression during carcinoma progression may enhance tumor cell invasiveness." (PMID 26869927, 2016). "FGFR3, LYPD3, PVRL4, SDC1, and TACSTD2 exhibited significantly elevated expression levels in squamous cell carcinoma relative to adenocarcinoma." (PMID 40046734, 2025). "However, Mad expression was lost in palisading basal carcinoma cells and poorly differentiated squamous cell carcinomas, which lacked the epithelial differentiation marker syndecan-1." (PMID 8645578, 1996). "Low Sdc-1 expression was observed in the progression of cervical intraepithelial neoplasia (CIN) grade I to grade III, while in poorly differentiated squamous cell carcinomas, Sdc-1 was almost absent." (PMID 35155241, 2022).
fibrosarcoma (15 papers, 2011 to 2023). A malignant mesenchymal fibroblastic neoplasm affecting the soft tissue and bone. "A similar syndecan-1-associated inhibition of fibrosarcoma cell motility was also seen with time-lapse microscopy, where the total distance moved was unaltered in the overexpressing cells, whereas the final displacement was decreased." (PMID 21731601, 2011). "A truncated variant of SDC1 was shown to stimulate metastasis of fibrosarcoma in a mouse model." (PMID 34570764, 2021). "Interestingly, in STAV-AB malignant mesothelioma and B6FS fibrosarcoma cells overexpression of the same full length and truncated syndecan-1 constructs exhibit opposite effects, causing reduced cell proliferation by the elongation of G1 and S phases of the cell cycle and retarded migration." (PMID 22745764, 2012). "Using fibrosarcoma cells, a study by Szatmári and co-workers showed that tumor cells also internalize SDC1, and their proliferation is prevented by the nuclear translocation of this PG." (PMID 36980680, 2023). "Nuclear glypican (Gpc) has been found in neurons and glioma cells, syndecan-4 (Sdc-4) in cardiomyocytes, Sdc-1 in fibrosarcoma cells, and Sdc-2 in the nucleus of tumour cells in osteochondromas." (PMID 33922532, 2021). "To provide new insight into the regulatory pathways governed by nuclear syndecan-1 we performed transcriptomic and proteomic screenings of the B6FS fibrosarcoma cells transfected with the three syndecan-1 constructs." (PMID 29216821, 2017). "We used a fibrosarcoma model to dissect the functions of syndecan-1 related to the nucleus and separate them from functions related to the cell-surface." (PMID 29216821, 2017). "With the same two fibrosarcoma cell-sub-lines (one transfected with FLs1 and the other with NLSdel), it was possible to separate the nuclear and cell-surface functions of syndecan-1." (PMID 29216821, 2017). "We showed that nuclear syndecan-1 inhibited proliferation and cell cycle progression in fibrosarcoma cells." (PMID 29216821, 2017). "To test the functions and molecular pathways related to nuclear localization, we separately studied the functions of syndecan-1 in the nucleus and on the cell surface by employing a fibrosarcoma model, with preserved and impaired nuclear localization." (PMID 29216821, 2017). "Nevertheless, following its overexpression syndecan-1 was found to translocate into the nucleus in human fibrosarcoma cells and this was dependent on a portion of the cytoplasmic C1 domain with the amino acid sequence RMKKK." (PMID 26378057, 2015). "The most extensively studied mesenchymal tumors addressing syndecan-1 expression are malignant mesothelioma and fibrosarcoma." (PMID 24392351, 2013). "Though the amount of syndecan-1 is usually low in fibrosarcoma, some samples and cell lines can express also this PG." (PMID 24392351, 2013). "In a recent study on HT1080 fibrosarcoma cell line syndecan-1 overexpression promoted proliferation along with the activation of genes driving the G1S transition, whereas in B6FS fibrosarcoma cell line the opposite effect was found." (PMID 23144729, 2012). "According to earlier studies, both syndecan-1 and syndecan-2 promote malignancy of HT-1080 human fibrosarcoma cells, by increasing the proliferation rate and the metastatic potential and migratory ability, respectively." (PMID 22745764, 2012). "We have recently shown that both full-length syndecan-1 and its specific protein domains inhibit the proliferation of human MM and fibrosarcoma cells." (PMID 21731601, 2011). "Overexpression of syndecan-1 also influences syndecan-4 expression, however, in a more variable manner as it is upregulated in MM cells but downregulated in fibrosarcoma cells." (PMID 21731601, 2011). "Increased invasiveness was observed in another fibrosarcoma cell line HT-1080 when transfected with the same full-length and 78 truncated syndecan-1 constructs as we used, and local growth was faster in the full-length syndecan-1 than the 78 transfectants." (PMID 21731601, 2011).
fibrosarcoma (continued). "Overexpression of the full-length syndecan-1 enhanced fibrosarcoma cell adhesion, and the high expresser gave a more pronounced effect, suggesting that syndecan-1 stimulates cell adhesion in a dose-dependent manner." (PMID 21731601, 2011). "Additionally, it was found with B6FS fibrosarcoma cells that nuclear translocation of SDC1 suppresses the mesenchymal phenotype and invasive behavior of these cells." (PMID 36980680, 2023). "In fibrosarcoma cells the location of syndecan-1 seems to be crucial." (PMID 24392351, 2013). "A recent study has demonstrated that both full-length and truncated syndecan-1 can modulate fibrosarcoma cell migration and adhesion, in which the extracellular domain is more important for promoting cell adhesion and the transmembrane and cytoplasmic domains in inhibiting cell migration." (PMID 22905270, 2012). "Further studies showed that nuclear translocation of SDC1 contributed to the repression of mesenchymal and invasive properties of human B6FS fibrosarcoma cells." (PMID 34208075, 2021). "Overexpression of full length SDC1 was significantly more effective than the RMKKKdel mutant of SDC1, which lacks the nuclear translocation signal, in repressing mesenchymal features of B6FS fibrosarcoma cells." (PMID 34208075, 2021). "Furthermore, nuclear translocation of syndecan-1 has been also reported to mediate TGF-β pathway activation and several transcription factors, thereby suppressing the growth of fibrosarcoma cells." (PMID 34326893, 2021). "Nuclear translocation of syndecan-1 hampered the proliferation of fibrosarcoma cells compared to the mutant lacking nuclear localization signal." (PMID 29216821, 2017). "In the present study, we demonstrated that overexpression of either full-length or truncated syndecan-1 lacking the ectodomain enhances proliferation, migration and spontaneous metastasis formation ability using the human fibrosarcoma cell line HT-1080." (PMID 22745764, 2012). "While the basal level of cell migration was not affected by transfection of the full-length syndecan-1 construct in fibrosarcoma cells, FBS-induced cell migration was hampered." (PMID 21731601, 2011). "We found that the full-length syndecan-1 and the remnants of syndecan-1 after shedding (the 78/EGFP construct), negatively regulated fibrosarcoma B6FS cell migration, and this can be partly due to the different phenotypes of these two fibrosarcoma cell lines." (PMID 21731601, 2011).
glioblastoma (15 papers, 2017 to 2026). The most malignant astrocytic tumor (WHO grade IV). "Exosomal miR-19b-3p was highly expressed in the serum of glioblastoma patients, and its exosome targets SDC1, VPS4B, and MYO5B were identified." (PMID 37569824, 2023). "In glioblastoma, overexpression of syndecan-1 leads to increased vascular growth factor (VEGF) signaling and enhanced angiogenesis via focal adhesion kinase (FAK) phosphorylation at tyrosine 397, extracellular signal-related kinase (ERK) pathway." (PMID 30135409, 2018). "In glioblastoma patients, overexpression of syndecan-1 is induced by a secreted glycoprotein, YKL-40." (PMID 30135409, 2018). "Previous research has shown that in glioblastoma, TGM2 enhances radioresistance by promoting the fusion of autophagosomes and lysosomes through its interaction with SDC1." (PMID 39375892, 2025). "Hypoxic glioblastoma cells generated more exosomes and a higher miR-182-5p content in exosomes than those in a normoxic state, improving angiogenesis, which was reversed by miR-182-5p knockdown, and its exosome targets RAB7A, ATP9A, and SDC1 were identified." (PMID 37569824, 2023).
breast tumors (14 papers, 2006 to 2025). "In another study, the expression of SDC1 was equivalent in the epithelium and stroma of breast tumors, but epithelial SDC1 expression was associated with negative ER status while stromal SDC1 expression was associated with positive ER status." (PMID 26293675, 2015). "It is also reported that several soluble cell surface proteins including E-cadherin (sE-cad), junctional adhesion molecule A (JAM-A) and Syndecan-1 (CD138) promote breast tumor metastasis." (PMID 36703228, 2023). "Collectively, these findings indicate that Sdc1 can stimulate breast tumor progression at many levels." (PMID 29976229, 2018). "On the other hand, invasive breast tumor cells stimulate SDC1 in the adjacent young and senescent fibroblasts by secreting TGF-β." (PMID 27434331, 2016). "The shift of SDC1 from epithelial to stromal cells during progression of breast tumors has been previously reported, and suggested to stimulate carcinoma growth and angiogenesis." (PMID 23327652, 2013). "However, contrasting results were observed in pancreatic and breast tumors, where the overexpression of SDC1 had the opposite effect." (PMID 38162504, 2023). "In contrast, syndecan-1 mRNA expression was higher in primary breast tumors vs. normal tissue (median: 12.62 vs. 11.05)." (PMID 29796177, 2018).